MMP9 (matrix metallopeptidase 9)
Diseases named in the same sentence as MMP9 in open-access papers (continued):
Sharing a sentence is not in itself a finding about the gene and the disease.
tumor (continued). "Moreover, TNF is a proinflammatory cytokine secreted by macrophages, T-lymphocytes and mastocytes, inducing an overexpression of MMP-2, MMP-3, MMP-7 and MMP-9 in the tumor microenvironment, contributing to the invasive capacity of malignant cells." (PMID 34204372, 2021). "This led to an increase in MMP-9 production and favored tumor growth through associated angiogenesis, without directly affecting the tumor cells." (PMID 34503058, 2021). "N2 TANs could contribute to tumor invasion and angiogenesis through the production of MMP9 and VEGF in the primary and metastatic sites." (PMID 35008550, 2021). "Among them, MMP-1, MMP-2, and MMP-9 are closely related to tumor invasion and metastasis." (PMID 35280249, 2021). "MMP10, MMP15 and MMP9 are found to be increased in GC and to correlate with poor patient prognosis During the metastasis process, tumour cells originating from primary tumour or metastases can be found circulating in blood, either single or in clusters." (PMID 33810350, 2021). "Furthermore, surface functionalization of MSNs was also possible using linkers that are specifically cleaved by matrix metalloproteinase (MMP9), to selectively target high-expressing MMP9 and tumor areas." (PMID 33499040, 2021). "Moreover, MDSCs contribute to tumor development and vascularization through enhancing MMP9 and differentiating into tumor endothelial cells." (PMID 34659412, 2021). "This MMP9/NGAL complex is related to tumor proliferation, metastasis, and chemotherapy resistance." (PMID 34976805, 2021). "However, MMP‐2 and MMP‐9 expression in tumour tissues were significantly upregulated and both were negatively correlated with RBM24 expression; P21 expression was inversely correlated with MMP‐2/MMP‐9 expression." (PMID 34709758, 2021). "Recent works have indicated that MMP9 increases tumour resistance to anti-PD-1 antibodies." (PMID 33954053, 2021). "Our study indirectly confirmed the promoting effect of MMP-9 on tumor angiogenesis." (PMID 33828938, 2021). "IHC of MMP9 revealed individual tumor cells with distinct cytoplasmic positivity." (PMID 33799999, 2021). "Accumulating studies confirmed that MMP-9 could facilitate the migration of tumor cells and cross-vascular invasion by dissolving extracellular matrix, thereby ultimately forming in situ and remote metastasis." (PMID 34178664, 2021). "Furthermore, MMP-9 supported pre-metastatic niche development upon induced overexpression in tumor stroma and, thus, can be related to ECM-mediated stimuli." (PMID 34073955, 2021). "However, matrix metalloproteinase-9 (MMP-9), a well-known cytokine for tumor migration and metastasis, was positive in most MG-63 cells." (PMID 34869325, 2021). "Most studies predominantly focused on associations between beta-blockers and mediator enzymes (such as MMP-9) instead of examining their direct effect on clinical (e.g., survival and tumor progression) or physiological endpoints (e.g., cell proliferation and cell migration)." (PMID 32172480, 2021). "The expressions of Ki67 and MMP-9 in the tumor tissues were detected by IHC staining." (PMID 34876144, 2021). "Interestingly, high-dose treatment (30 Gy) of the primary tumor decreased MMP-9 serum levels, improved tumor control and eliminated the amount of disseminating cells." (PMID 34055644, 2021). "However, previous report suggested that MMP-9 induces not only the awakening of dormant cancer cells in lung through extracellular matrix remodeling (ECM) but also outgrowth of tumor growth in the late phase of metastasis." (PMID 34163472, 2021). "In conclusion, these findings suggested that monocyte acted as a protective factor and MMP9/IGFBP1 played a vital role in tumor immune, which might become potential novel biomarkers and therapeutic targets for immunotherapy in ccRCC." (PMID 33758602, 2021). "However, our results showed that in VSCC- and SCC-PDSX, MMP9 expression was only observed in the tumor cells and was undetectable on BMDCs and stromal cells." (PMID 35008304, 2021).
tumor (continued). "Besides, the down-regulation of matrix metalloprotein 2 (MMP2) and MMP9 also reduced the rate of tumor metastasis." (PMID 34051801, 2021). "Compared with neutrophils in blood, tumor associated neutrophils (TANs) around tumor can produce more cytokines and promote tumor progression by ways of secreting Matrix Metallopeptidase 9 (MMP-9) to advance the degradation of extracellular matrix and release vascular endothelial growth." (PMID 34925510, 2021). "Besides, MMP-9, highly expressed in many tumor cells, is a proteolytic enzyme closely related to tumor metastasis, invasion, and adhesion, and can degrade extracellular matrix, thus promoting cell migration." (PMID 33833775, 2021). "Notably, MMP-9 is essential for tumor invasion, metastasis and angiogenesis, and considered as a valid biomarker for cancers." (PMID 33534099, 2021). "MMP9 overexpression was more frequent in patients with larger tumor sizes." (PMID 33568081, 2021). "Most likely, the effect of upregulated stromal Mmp9 and Bv8 may be neglectable because the primary tumor itself is a rich source of pro-angiogenic and pro-inflammatory factors." (PMID 34282521, 2021). "Moreover, the secretion of MMP-2 and MMP-9 is significantly inhibited, thereby inhibiting the migration and invasion of tumour cells." (PMID 34539401, 2021). "Additionally, the expression of MMP-9 (matrix metalloproteinase-9) of tumor tissue in the LF group increased." (PMID 34819565, 2021). "In addition, higher level of MMP9 correlated with earlier distant metastasis and higher tumor stage, which predicted poorer prognosis in HCC." (PMID 34239873, 2021). "Interestingly, a high variability of MMP2 and MMP9 activity levels was recorded between different patients, suggesting their possible role in tumor progression." (PMID 34830271, 2021). "Conversely, promoting MMP-9 can enhance the proliferation and migration of tumor." (PMID 34869390, 2021). "In addition, in in vitro models, SCFAs have shown to decrease the levels of pro-inflammatory cytokines and proteins like MMP-9, which are well documented to promote tumor invasion." (PMID 32722632, 2020). "MMP-9 has been reported to play a crucial part in the invasion/metastases of tumor cells." (PMID 32377273, 2020). "Moreover, the activation of ERK can increase the expression of invasion-related genes, including MMP-2 and MMP-9, thereby promoting the invasion and migration of tumor cells." (PMID 32049100, 2020). "Furthermore, depletion of NOX4, ANGPTL4, MMP-1, and MMP-9 in CRC cells significantly blocked OA-enhanced metastatic seeding of tumor cells in lungs." (PMID 32641980, 2020). "Moreover, MMP2 and MMP9, as proteolytic enzymes, are involved in the degradation of extracellular matrices, which play a crucial role in tumor invasion and metastasis." (PMID 33024414, 2020). "The findings of MMP-9 presence not only in the primary tumour but also in the tumour budding strongly supports the hypothesis that proteolytic activity helps to create an “infiltrative tumour border configuration”." (PMID 32403316, 2020). "Similarly, Szalay and colleagues showed that intratumoral administration of GLV-1h255, a VV expressing MMP9, in mice bearing prostate tumors enhanced collagen IV degradation, viral replication, and tumor regression." (PMID 33167307, 2020). "Moreover, NF-kB is further activated by inflammatory cytokines which are its transcriptional targets, thereby promoting MMP-9 expression by both the transformed and normal cells constituting the tumor mass." (PMID 32630531, 2020). "Both MMP3 and MMP9 act in synergy to promote tumor invasion and metastasis." (PMID 32517128, 2020). "Moreover, activation of Jak/STAT3 signaling pathway has been shown to regulate MMP-9 expression in tumor invasion and metastasis." (PMID 33228717, 2020).
tumor (continued). "MMP9 inhibitors lead to a decrease in the number of tumor colonies, but tumors in vivo are larger and more vascularized, which may provide a rationale for the coadministration of MMP inhibitors and antiangiogenic agents." (PMID 33182665, 2020). "MMP-9 is involved in cancer metastasis and tumor-induced angiogenesis." (PMID 32408577, 2020). "c-Myc overexpression sustains M2 polarization, a characteristic of human tumor-associated macrophages (TAMs), and regulates the expression of vascular endothelial growth factor (VEGF), matrix metallopeptidase 9 (MMP9), HIF-1α, and transforming growth factor beta (TGF-β)." (PMID 31906500, 2020). "MMP9 signal was mostly localised to the tumour edge, that is, the invasive margin." (PMID 32655131, 2020). "The aim of this study was to determine whether elevated MMP9 expression at mRNA and protein level correlated with tumour grade, BC morphology, cytoskeletal modulators and patient outcome using a large clinical data set with long-term follow-up." (PMID 32445177, 2020). "MMP9 plays an important role in tumor invasion and metastasis." (PMID 32856853, 2020). "Additionally, the protein expressions of MMP-2 and MMP-9, crucial for tumor invasion, exhibited an identical pattern of Jagged2 among the four groups." (PMID 32792862, 2020). "Moreover, MMP‐2 and MMP‐9 expressions, markers for tumor invasiveness, were also increased in A549‐IR cells." (PMID 32328272, 2020). "MMP9 was critical for tumor angiogenesis and extracellular matrix remodeling." (PMID 33456675, 2020). "Indeed, we have shown that both MMP3 and MMP9 were expressed at high levels in LuM1 cells and proved their important roles in tumor progression." (PMID 32429403, 2020). "In other tissues, CAT has previously been capable to activate pro–MMP-2 in human tumor cell invasion and together with MMP-9 may enhance TGFβ signaling in a tumor murine model." (PMID 33195599, 2020). "Besides, CD248 enhanced the adhesion to the extracellular matrix, and activated the matrix metalloproteinase 9 (MMP9) in tumor metastasis." (PMID 33585235, 2020). "In the current study, we revealed a tumor-promoting effect of the MMP9/PAR1 axis, suggesting that targeting this axis may have clinical benefit." (PMID 32809114, 2020). "Additionally, results of western blot presented that the protein levels of MAPK1, c-Myc and MMP9 in tumor tissues were significantly reduced but Bax expression was enhanced in sh-LINC00483 group in comparison to those in sh-NC group." (PMID 32293550, 2020). "Once the dynamic balance between TIMP1 and MMP9 is broken, it may promote tumor invasion and metastasis." (PMID 33144895, 2020). "These carotenoids can reverse EMT and also significantly reduced N-cadherin, beta-catenin expression, increased expression of E-cadherin, and modulate matrix metalloproteinase 2, 9 (MMP2 and MMP9), and urokinase-type plasminogen activator expression/activity in tumor cells." (PMID 32405344, 2020). "MMP-9 is involved in basement membrane degradation that furthers tumor invasion and metastases." (PMID 32085733, 2020). "Furthermore, it has been reported that inflammatory cell MMP9 initiates the onset of tumor neovascularization during which there exists functional links between VEGF and MMPs including MMP9." (PMID 32855630, 2020). "Despite this, analysis of each MMP band in each of the three independent experiments showed that DDR1-IN-1 significantly reduced by ~ 25% the expression of the active MMP9 (~ 82KDa) in the secretomes from basal KCs cultures, and by ~ 50% in the secretomes from tumor-activated KCs." (PMID 33110221, 2020). "The mature and activated MMP-9 could facilitate the invasion and metastasis of tumours through gelatine in the extracellular matrix." (PMID 32209138, 2020). "Among MMPs, MMP-2 and MMP-9 levels are positively correlated to tumor vessel density." (PMID 32528888, 2020). "It is also reported that chymase increases the expression of MMP-9 in tumor cells." (PMID 31256327, 2020).
tumor (continued). "Similarly, snail inhibits the expression of E-cadherin through the SMAD pathway, increases the expression of MMP9, increases tumor angiogenesis, and promotes cell survival via the MAPK and PI3K pathways." (PMID 32630820, 2020). "Our study suggests that the tumor-suppressive role of MMP9 could be tissue specific and/or disease specific." (PMID 32943603, 2020). "There were convincing proofs that over-activation of HIF-1 could lead to aggressive proliferation and invasion of tumor cells, which was achieved via alteration of MMP9, VEGF and NDRG1 expressions." (PMID 32143722, 2020). "Additionally, before tumor cell arrival, neutrophils provided lungs of mice bearing mammary adenocarcinomas with MMP-9 to promote vascular remodeling, thereby forming pre-metastatic niche." (PMID 32422991, 2020). "MMP9 was also highly expressed in basal type tumours over luminal A and luminal B tumours." (PMID 32445177, 2020). "Furthermore, as patients with the worst clinical outcome showed higher expression of VEGFR-1 or coexpression of VEGFR-1 and MMP9 in the tumor than in peritumoral tissues, VEGFR-1 has been proposed as a prognostic marker for hepatocellular carcinoma." (PMID 32085654, 2020). "Additionally, AP-1 increased tumor invasion and metastasis of through regulating matrix metalloproteinase 9 (MMP-9) through interaction with MMP-9 promoter." (PMID 32856873, 2020). "It has been reported that TGF-β1 enhances tumor invasion by stimulating MMPs, such as MMP-9 33-35." (PMID 32328185, 2020). "Here we show that gal-8 KO mice manifest reduced expression of MMP9 that could contribute to their resistance to tumor development." (PMID 32355198, 2020). "And the knockdown of the MMP-9 gene could also significantly decrease the metastatic distance and number of metastatic tumor cells or lesions in vivo and suppress the metastasis rate in xenografted zebrafish." (PMID 32382550, 2020). "Furthermore, the tumor cell invasion is facilitated by the activation of the Src/slug signaling that induces the expression of MMP-9/-2 and vimentin during the EMT." (PMID 32466169, 2020). "Fluorescence signal indicative of active MMP9 laterally increased with tumour growth in controls." (PMID 32655131, 2020). "TNF-α upregulates the emission of matrix metalloproteinase-9 (MMP-9) from tumor cells." (PMID 32194791, 2020). "Besides, MMP2 and MMP9 can degrade collagen in the basement membrane of blood vessels, which is involved in angiogenesis, tumor invasion and migration." (PMID 33098235, 2020). "Therefore, in the present study, MMP9 expression is a potent marker of tumor progression, recurrence, and metastatic potential, which we aimed to suppress." (PMID 32102440, 2020). "LncRNA PTCSC3 was significantly suppressed in PTC tumor tissue and it could affect PTC predisposition and carcinogenesis through downregulating the MMP-9 and VEGF expression via the S100A4 pathway." (PMID 32284745, 2020). "In summary, the knockdown of MMP-9 in OSCC cells might inhibit tumor cell metastasis and invasion and reduce the metastasis rate of xenografted zebrafish." (PMID 32382550, 2020). "The CA4-loaded nanocarriers could disrupt tumor blood vasculature and selectively enhance MMP9 expression in tumors to promote the accumulation of doxorubicin, leading to effective treatment of 4T1 and C26 tumors." (PMID 32292515, 2020). "Besides, the tumor tissues of the SEM patients with stages II–III shows a higher level of MMP9 than those SEM patients with stage I. What’s more, a negative correlation was found between miR-483-3p and MMP9 expression." (PMID 33659208, 2020). "MIF-induced CCL4 and MMP9 production in TANs may have tumor autonomous effects by promoting lymphangiogenesis as well as tumor-stromal remodeling." (PMID 33324425, 2020). "Mounting evidence illustrated that MMP-9 (gelatinase B) might play a significant role in GCT tumor progression and invasion." (PMID 33207819, 2020).
tumor (continued). "Moreover, KLK7 has been reported as an activator of matrix metalloproteinase-9 (MMP-9) in carcinomas, thus displaying a key role in processes of tumor cell migration, invasion, and angiogenesis, further implying the involvement of KLK7 in tumor progression." (PMID 33087135, 2020). "In addition, many studies have identified that MMP2 and MMP9 are closely related to tumour migration and invasion and explained the mechanism." (PMID 33128353, 2020). "MMP-9 plays an important role in the invasion and metastasis of tumours." (PMID 32209138, 2020). "Furthermore, we validated that the expression of MMP9 by RT-qPCR in the 20 pairs of tumor and paracarcinoma tissues." (PMID 33659208, 2020). "MMP-2 and MMP-9 activity is important in initiating tumor invasion." (PMID 32102512, 2020). "MMP9 cleave the basement membrane type IV collagen and promote tumour invasion and metastasis." (PMID 32445177, 2020). "Moreover, in tumor tissue, MMP-9 triggers the formation of new lymphatic vessels, providing additional routes for cancer metastasis." (PMID 32630531, 2020). "Moreover, gavage administration of SG inhibited the protein level of MMP2 and MMP9 in the tumor tissues of the xenograft model." (PMID 32508048, 2020). "Treatment of nude mice bearing subcutaneously injected breast cancer cells, with an adenovirus carrying the MMP-9 gene resulted in a significant reduction in tumour growth and an increase in intra-tumoural endostatin; a proteolytic fragment of collagen type XVIII." (PMID 33187209, 2020). "In addition, curcumin administration increased caspase-3 activity and reduced MMP-2 and MMP-9 activity within the tumor tissue, indicating that curcumin can promote apoptosis and inhibit MMP secretion at the location of the tumor to prevent cancer progression." (PMID 33182828, 2020). "MMP2 and MMP9 are the two critical MMPs that mediate tumor cell invasion." (PMID 32420351, 2020). "The expansion and recruitment of MDSCs to the tumor sites is also mediated by MMP9." (PMID 32849585, 2020). "The presence of heparanase in the nucleus leads to loss of the heparan sulfate proteoglycan syndecan-1 from the nucleus, resulting in enhanced histone acetyltransferase (HAT) activity and upregulation of expression of VEGF and MMP9, two genes that contribute to an aggressive tumor phenotype." (PMID 32899927, 2020). "Therefore, CD147 expression on tumor cell surfaces is, in general, considered to be increased, which leads to the stimulation of MMP-9 activity." (PMID 32377273, 2020). "It should be noted that also other proteases, which are released by macrophages, including MMP2 and MMP9, might play a role in tumor-induced damages of the sciatic nerve." (PMID 32013137, 2020). "Moreover, a study showed that EP3 receptor signaling on endothelial cells is essential for the MMP-9 upregulation that enhances tumor metastasis and angiogenesis." (PMID 33228717, 2020). "The same study also revealed MMP-9-expressing NK cells as important contributors of tumor angiogenesis, and that inhibition of MMP-9 with immunotherapy could help repolarize NK from pro-angiogenesis to anti-tumor effector cells." (PMID 32063906, 2020). "Both CCND2 and MMP9 transcripts harbor 3′-UTR recognition sites for miR-204 suggesting that miR-204 may play a tumor suppressor role in RB progression by targeting CCND2 and MMP9." (PMID 32070426, 2020). "Of them, MMPs, MMP2, MMP3 and MMP9 could induce tumor cell invasion and migration by promoting the degradation of extracellular matrix, such as collagen." (PMID 32924971, 2020). "Moreover, acidic tumour microenvironment promotes the activation of proteinases such as matrix metalloproteinase 9 (MMP-9) and enhances the invasiveness of cancer." (PMID 32843908, 2020). "A strong expression of MMP-9 and a strong upregulation of the MMP-9 protein in the vicinity of the extravasation of cancer cells, associated with activated astrocytes surrounding the tumor cells, have been observed." (PMID 31900168, 2020).